IL6 (interleukin 6)
Diseases named in the same sentence as IL6 in open-access papers (continued):
Sharing a sentence is not in itself a finding about the gene and the disease.
cancer (continued). "In vitro evidence supporting that Ruxolitinib induced decreases in cytokine levels and disruption of STAT3 activation via upstream signaling suggests a role for Ruxolitinib in cancer cases characterized by elevated IL-6 levels." (PMID 38339245, 2024). "Signaling by the IL-6/JAK/STAT3 axis is prominent in many human cancers and regulates various cellular functions relevant to cancer advancement, such as inflammation, cell survival, and proliferation." (PMID 38979413, 2024). "Some mammalian macrophages secrete cytokines such as globule-EGF factor 8 and IL-6, which leads to the tumorigenicity of cancer stem cells." (PMID 39684820, 2024). "IL-6 and IL-22, two cytokines that activate STAT3, enhanced XIAP in cancer cells, and such induction was attenuated in SMAD7-deficient cells." (PMID 39001432, 2024). "Currently, the predictive capabilities evaluation of IL-6 in cancer mostly focuses on treatment outcomes or survival status, making it one of the most discussed prognostic markers for NSCLC patients." (PMID 38339264, 2024). "In cancer studies, overexpressed STAT3 has been associated with IL-6–induced MMP9 release, which favors invasiveness/metastasis." (PMID 37982695, 2024). "In this context, higher levels of IL-6, a pleiotropic cytokine involved in both inflammatory responses and cancer development, have been observed in patients with various types of myeloid cancer." (PMID 38337668, 2024). "Most studies and therapeutic explorations on IL-6 in cancer cachexia has focused on its functions in peripheral organs, including the skeletal muscle, liver, and gut17." (PMID 38824130, 2024). "The relative luciferase activity was compared to the cancer cells transfected with the IL-6 3′UTR reporter clone alone." (PMID 38338683, 2024). "The acquired findings were statistically significant, demonstrating an increase in IL-6 levels with the onset of cancer." (PMID 38962618, 2024). "This panel yielded an AUC of 0.80, significantly surpassing the performance of IL-6 and IL-8 when used alone (AUC = 0.70 or 0.75, all p < 0.05) to distinguish WA cancer patients from their healthy counterparts." (PMID 38276239, 2024). "IL6 enhances cell cycle progression in various cells, particularly cancer cells, by activating gene expression for cell growth, proliferation, survival, and differentiation." (PMID 39766086, 2024). "Autoantibodies to IL-6IF occur in a higher concentration in healthy individuals than in advanced cancer patients, who thereby have less efficient protection against pathological IL-6 production." (PMID 39518029, 2024). "Taken together, these mechanisms make the IL-6 axis an attractive target for the unique characteristics of PC as a specific pattern of metastatic disease and cancer progression." (PMID 38689325, 2024). "In pathological conditions of obesity and cancer, IL-6 levels secreted by adipocytes are significantly increased." (PMID 38800384, 2024). "IL-6, present in high concentrations in various cancer types, correlates with cancer progression and therapeutic resistance." (PMID 38225613, 2024). "Since E2F1 orchestrates the immunomodulatory network via IL-6, we first investigated the effect of IL-6 on the cancer-immune crosstalk." (PMID 39544930, 2024). "IL-6 has been found to be deregulated in cancer, with its overexpression reported in almost all types of tumors." (PMID 39502692, 2024). "In this paper, a large amount of IL-6 was found to be produced by PBMCs in cultures from cancer patients." (PMID 39518029, 2024). "As dictated earlier, IL-6 activates STAT3 signaling to help cancer cells achieve their proliferative potential." (PMID 38279220, 2024). "In fact, as early as 1993, it was claimed that IL-6 monoclonal antibody or IL-6 receptor antagonist treatment significantly inhibited the development of cancer cachexia in homozygous mice." (PMID 39703501, 2024).
cancer (continued). "CXCR-2 ligands include CXCL-1, CXCL-2, CXCL-3, CXCL-5, IL-6, CXCL-7 and IL-8, and overall CXCLs/CXCR-2 pathway is implicated in cancer and inflammation." (PMID 38672477, 2024). "Then, IL-6 binds to IL-6R on the surface of cancer cells to induce STAT3 axis for cancer progression." (PMID 39014491, 2024). "The results also showed that cytokine and receptor activity were enriched in AML, further validating the role of inflammatory signals such as IL-6 or TNF-α in the development of cancer stem cells." (PMID 39877157, 2024). "In cancer patients receiving n-3 LCPUFAs from fish oil supplements, inflammatory cytokines, including interleukin- 6 (IL-6), C-reactive protein (CRP) and tumor necrosis factor-alpha (TNFα), were found to be lower than those in control groups." (PMID 38308227, 2024). "Factors such as TGF-β, HIF1α, β-catenin, IL-6, caveolin-1, vimentin, and nucleic acids, including miRNAs, which are transported with the help of exosomes secreted by cancer cells, play an important role in the mobilization of EMT regulators." (PMID 38473285, 2024). "Given the IL-6’s impact on cancer-related processes, therapeutic modulation of its signalling axis holds promise." (PMID 39676864, 2024). "The PGCCs‐derived IL‐6 stimulates fibroblasts to increase collagen production, enrichment of the GPR77+/CD10+ cancer‐associated fibroblasts (CAFs) subpopulation and VEGF expression." (PMID 38362620, 2024). "IL-6 secretion was measured by ELISA in OSCC cell lines (SAS, HSC2, and HSC3), cancer-associated fibroblasts (CAFs), and normal fibroblasts (NFs)." (PMID 38510850, 2024). "Taken together, the Yin group here has identified a hypoxia-triggered HIF-1α/miR-338-5p/IL-6 feedback loop, offering a direction for future research in cancer therapy." (PMID 37588219, 2024). "In our analysis, co-culture of mouse CAFs with PC-3 or PC-42 cancer cells upregulated the secretion of mouse IL-6 and LIF from CAFs compared with monoculture of CAFs, and EBET-1055 treatment canceled the upregulation." (PMID 38467634, 2024). "Interleukin-6 (IL-6) is a proinflammatory cytokine that is involved in the development of various cancers including OSCC." (PMID 39099925, 2024). "B7 stands out for its ability to significantly reduce cancer cell proliferation in A431, A549, and H1299 cell lines and lower the levels of inflammatory cytokines IL-6 and TNF-α." (PMID 38562527, 2024). "Regarding metabolic and cardiovascular biomarkers and cancer treatment, there were positive correlations between IL-6 and length of steroid therapy, and between IL-10 and cisplatin and ifosfamide total doses." (PMID 38254811, 2024). "Chronic inflammation is one of the major predisposing factors in cancer progression and is indicated by increased plasma levels of C-reactive protein (CRP), interleukin 6, and tumor necrosis factor-alpha." (PMID 38509114, 2024). "Cancer cells undergo EMT through IL-6 secretion to transform into stem-like cells with self-renewal capabilities in hypoxic conditions." (PMID 39796695, 2024). "Serum CRP can cause systemic inflammation by secreting various pro-inflammatory cytokines, such as IL-1, IL-6 and TNF-α, resulting in the gradual loss of important protein components in host, leading to the death of cancer patients." (PMID 38184747, 2024). "Interleukin-6 receptor (IL-6R), stimulated by IL-6, triggers intricate cell functions including immune cell activation, hematopoietic stem cell differentiation, cancers, and inflammatory bowel diseases." (PMID 38256960, 2024). "Interleukin 6 for example, directly impacts leptin and ghrelin, which in turn contributes to the depressed appetite in cancer cachexia patients." (PMID 38744744, 2024). "IL6/IL8 secreted CAFs and associated JAK2-STAT3 signaling result in cancer relapse and poor prognosis." (PMID 38320998, 2024).
cancer (continued). "Together, these results show that EVP-induced secretion of IL-6 by lung IMs is required for vascular leakiness to support extravasation of circulating cancer cells and metastasis formation." (PMID 38853850, 2024). "This process is further facilitated by the presence of TNF-α, another cytokine that is often upregulated in cancer and can synergize with IL-6 to enhance ICAM-1 expression." (PMID 38689325, 2024). "IL-6 is of major importance in the pathogenesis of a large number of severe diseases such as cancer and chronic inflammation." (PMID 39518029, 2024). "Studies have shown an increase in various inflammatory markers in the peripheral circulation during cancer, including IL-1, IL-6, IL-1β, and TNF-α in different types of cancer." (PMID 38473351, 2024). "IL-6 promotes cancer cell proliferation, survival, and metastasis through the activation of the JAK/STAT3, PI3K/AKT, and MAPK signaling pathways." (PMID 39335659, 2024). "These cytokines participate in angiogenesis and play an executive role in cancer cell proliferation and metastasis by controlling NF-κB, IL-6/JAK/STAT3, PI3K-PKB/Akt, Ras/Raf, JNK, MAPK, and AKT pathways." (PMID 39664179, 2024). "Accumulating evidence proved that components of the SASP, such as IL‐8 or IL‐6, are relative to cancer chemotherapy resistance." (PMID 37964494, 2024). "Several cancers, including CC, have been shown to activate the IL-6/STAT3 signaling pathway to support cancer cell survival and invasive expansion." (PMID 38511067, 2024). "The nature of IL-6-inducing factors was further explored by identifying protein fractions in cancer patient urine." (PMID 39518029, 2024). "A positive correlation between increased IL-6 levels and pain intensity in cancer patients undergoing chemotherapy has been found in clinical practice." (PMID 38940936, 2024). "Various inflammatory factors that affect the occurrence and progression of cancer, including IL-6, IL-1, and TNF-a dysregulation, can all affect cholesterol synthesis." (PMID 38605235, 2024). "IL-6 is a key performer in the development of cancer, cytokine storms, autoimmune illnesses, and chronic inflammatory diseases." (PMID 37971510, 2024). "A combination of anti-IL6 blockade and checkpoint inhibitors is promising to enhance immune response in cancer patients." (PMID 39766086, 2024). "The major pro-inflammatory cytokines include IL-1β, IL-6, and TNF-α, the continuous intensification of inflammation is an important cause of cancer." (PMID 38572238, 2024). "Here, cancer cell-derived cytokines educate myeloid cells to reciprocate by secreting oncostatin M and IL-6, which, in turn, induces cancer-stem cell (CSC) properties in the malignant cells." (PMID 38571887, 2024). "Future studies should include in vivo experiments with IL-6 neutralization, comparing the effects of 5-FU treatment on tumors co-inoculated with MKN45 cells and ASCs to further clarify the role of IL-6 signaling in cancer stemness and resistance." (PMID 39766174, 2024). "The resulting effect is the proliferation of cancer cells and the production of IL-6, anti-apoptotic factors, and other tumorigenic effectors." (PMID 38279220, 2024). "Since IL-6 has broad and robust effects on maintaining an inflammatory milieu and promoting cancer development, the in situ fibroblast niche boosts NSCLC metastasis and progression." (PMID 38459511, 2024). "Inflammatory pathways mediated by interleukin‐6 (IL‐6) play a crucial role in the development of cancer cachexia." (PMID 39523982, 2024). "According to studies, BC cells express greater amounts of IL-6, which functions as a cancer promoter." (PMID 38609357, 2024). "High interleukin-6 levels correlate with diseases like cancer, autoimmune disorders, and infections." (PMID 39229261, 2024). "In our analysis, we compared CRP, as a general marker of systemic inflammation, and IL-6, as a specific factor in emergence of cancer cachexia, as two biomarkers that would be easily accessible in routine clinical practice." (PMID 38539528, 2024).
cancer (continued). "Atezolizumab, a monoclonal antibody intended the PD-L1, activates the immune system to combat cancer cells, leading to the release of pro-inflammatory cytokines like IL-6 and TNF-α." (PMID 38367261, 2024). "Blocking IL6 signaling is a potential strategy for treating cancers characterized by pathological overproduction of IL6." (PMID 38727303, 2024). "IL-6 mediates the release of hepcidin from the liver, which inhibits iron absorption and iron release to prevent cancer cells from utilizing iron, thereby reducing erythropoiesis." (PMID 39744624, 2024). "Pro-inflammatory stimulation of IL-6 underlines signalling via JAK/STAT3, which promote EMT in multiple cancer types." (PMID 39348343, 2024). "As in other cancer types, combinatorial activity of IL-6 pathway inhibition with cytotoxic chemotherapy has also been explored." (PMID 38689325, 2024). "After the discovery of IL-6, its role in promoting the growth, invasion, and spread of cancer has been widely recognized." (PMID 38828409, 2024). "Activation of IL6 through STAT3 (signal transducer and activator of transcription 3) in cancer-associated fibroblasts (CAF) has been shown to enhance the resistance of CCA to gemcitabine." (PMID 38672199, 2024). "IL-6 signaling pathway and IFNγ response were most significantly enriched in Bcl6 knockout cancer cells." (PMID 38956432, 2024). "When IL-6 downregulates PPAR α, it restricts the ketogenic effect, leading to greater energy deficiency in cancer patients." (PMID 38828409, 2024). "The signaling pathway of IL-6 has been demonstrated to control the characteristics of stem cells that are responsible for cancer initiation and progression." (PMID 38891090, 2024). "Interleukin 6 (IL-6) is a cytokine that potentially contributes to the development of both chronic and acute cancer stem cells (CSCs)." (PMID 38891090, 2024). "To determine the role of IL-6 in mediating the acquisition of cancer stemness enhanced by ASCs, we investigated the effect of IL-6 neutralizing antibody on the sphere-forming capacity of GC cells." (PMID 39766174, 2024). "In particular, IL-2, TNF-α, and IL-6 play crucial roles in the immune response to inflammation as well as cancer." (PMID 39317690, 2024). "NF-κB is one of the most well-known molecular pathways involved in cancer and has been considered a prototypical pro-inflammatory signaling pathway, activated by cytokines such as interleukin 6 (IL-6) and TNF-α." (PMID 39596471, 2024). "IL-6 cytokine is also involved both in diabetes and cancer by controlling glucose homeostasis, insulin sensitivity as well as tumorigenesis in different cancers." (PMID 39333445, 2024). "This is in line with previous studies showing that IL-6 mediates cellular cross-talk in the microenvironment in other cancer types." (PMID 38422751, 2024). "These M1-like TAMs promote EMT and cancer stem cell formation through the IL-6/Jak/Stat3/THBS-1 axis." (PMID 39200273, 2024). "The aberrant activation of the IL6/GP130/STAT3 signaling pathway and the IL6 feed‐forward loop formation are the drivers of tumorigenesis in many types of cancer, including NSCLC." (PMID 39152779, 2024). "Tumors expressing β-catenin suppress the production of CCL4, thereby limiting DC infiltration, while IL-6 from immune and cancer cells inhibits cDC differentiation." (PMID 38785789, 2024). "Substantial evidence supports the anti-tumorigenic potential of SKM-derived IL-6, including its role in the SKM contractile activity-induced mitigation of cancer risk." (PMID 38928185, 2024). "Cancer cells enhance IL-6 production by fibroblasts, and IL-6 increases vascular endothelial growth factor (VEGF) production, promoting angiogenesis." (PMID 38510850, 2024). "Subsequently, we knocked down IL-6 in CAFs or cancer cells separately and established a transwell coculture system to measure IL-6 secretion level." (PMID 38459511, 2024).
cancer (continued). "Activated p38α has also been shown to support cell survival via anti-apoptotic interleukin-6 (IL-6) inflammatory signals and enable DNA repair after chemotherapy, resulting in drug resistance in cancer cells." (PMID 38806469, 2024). "Reduced sleep in cancer patients was associated with elevated levels of CRP and interleukin-6 (IL-6), leading to an increase in the body's inflammatory levels." (PMID 39592977, 2024). "The production of IL-6 by PBMCs from cancer patients in vitro means that either the producing cells were triggered in vivo and maintained this status in cultures or that there is a serum factor which stimulates the production of IL-6." (PMID 39518029, 2024). "Research has shown that exercise-induced IL-6 possesses both direct and indirect anti-cancer properties." (PMID 39346906, 2024). "The results showed a correlation between IL-6 and the poor efficacy of Atezolizumab in advanced cancer patients." (PMID 39101140, 2024). "Taken together, the data indicate a strong commonality between diverse cancer types, not only in IL-6, but in the major cytokines and chemokines comprising the pleural secretomic milieu." (PMID 39114667, 2024). "Cytokines like IL-6 have been reported to influence metabolic processes in cancer cells and alter LNCaPs response to other soluble factors." (PMID 39273225, 2024). "The novel findings show for the first time that gold nanoparticles can inhibit interleukin-6 mRNA/protein secretion by upregulating miR-26a-5p and deactivating the RelA and NF-κBp50 transcription pathways in cancer cells." (PMID 38338683, 2024). "IL‐6 plasma concentrations also correlate with poor treatment response and increased mortality in cancer patients." (PMID 38302863, 2024). "Recent studies on cancer cell conditioned media indicates that interleukin‐6 (IL6) is highly expressed." (PMID 39136147, 2024). "It is noteworthy that IL-6 plays a pivotal role in the progression of several cancers, including numerous forms of leukemia, via this pathway." (PMID 38256942, 2024). "Evidence has revealed anti-IL-6 antibodies were responsible for promising strategies to treat various cancers." (PMID 38256960, 2024). "On the contrary, IL-6, one of the most investigated cytokines in cancer, was detected in MSCs and was virtually missing from A431 cultures; however, in co-cultures its secretion increased two-fold." (PMID 38674102, 2024). "In a modified Boyden invasion chamber assay, IL-6 was found to correlate with an increased invasion of cancer cells." (PMID 38671854, 2024). "Of the cytokines investigated, IL-6 was notably the only cytokine associated with decreased objective response rate (ORR) and worse cancer-specific and all-cause mortality." (PMID 39403930, 2024). "This leads to the exacerbation of intercellular cytokine signaling including IL-6 and deregulation of the transcriptional landscape in immune and cancer cells." (PMID 39544930, 2024). "One of the best-researched molecules in cancer progression is interleukin 6 (IL-6), which is crucial for proliferation, inflammation, and metabolism." (PMID 38455762, 2024). "Vice versa, an overproduction of IL-6 and dysregulation of the IL-6 signaling pathways can result in inflammatory and autoimmune disorders as well as in the development of cancer, suggesting that IL-6 plays an important role in the human cytokine network." (PMID 39272983, 2024). "Analysis of mRNA and protein expression found that treatment with huB12-MMAE resulted in the increased secretion of the proinflammatory cytokines IL6 and IL8 by CAFs and an associated increase in expression of proinflammatory genes in cancer cells." (PMID 38747612, 2024). "We conclude that IL-6 has been identified as a key oncogene in the development of tumors and their spread in several types of cancers, including OSCC." (PMID 39099925, 2024).